PML (PML nuclear body scaffold)
Diseases named in the same sentence as PML in open-access papers (continued):
Sharing a sentence is not in itself a finding about the gene and the disease.
lung fibrosis (1 paper, 2014). "Future experiments, are planned that will employ PML KO mice in murine models of pulmonary fibrosis." (PMID 24762191, 2014). "Moreover, low dose ATO blocks bleomycin-induced lung fibrosis, and to date there is evidence that this correlates with a reduction in PML bodies." (PMID 24762191, 2014). "However, to date the role of PML in TGF-β1-induced FMD and lung fibrosis in vivo has not been addressed." (PMID 24762191, 2014).
lung squamous cell carcinomas (1 paper, 2017). "As expected, PML and BCL2 were not correlated (Spearman’s r = 0.092, p = 0.219) in the lung squamous cell carcinoma samples." (PMID 28332630, 2017).
lymphadenitis (1 paper, 2018). Acute or chronic inflammation of one or more lymph nodes. "Using the PLA assay, only one of 24 lymphadenitis lymph nodes displayed co-localization of TRF2 and PML signals in the control group." (PMID 29848986, 2018).
mesothelioma (1 paper, 2015). A usually malignant and aggressive neoplasm of the mesothelium which is often associated with exposure to asbestos. "Considering our results, we hypothesize that the PML-AKT-Ca2+ axis is directly involved in mesothelioma because a close relationship between AKT-PML and Ca2+-dependent apoptosis has already been demonstrated in other tumor types." (PMID 26156019, 2015).
non-Hodgkin lymphoma (1 paper, 2013). Distinct from Hodgkin lymphoma both morphologically and biologically, non-Hodgkin lymphoma (NHL) is characterized by the absence of Reed-Sternberg cells, can occur at any age, and usually presents as a localized or generalized lymphadenopathy associated with fever and weight loss. "The model provided gives a molecular explanation of the down-regulation of PML in non-Hodgkin lymphomas, suggesting a direct connection between E6AP expression and PML degradation in this disease." (PMID 23526763, 2013). "Finally, these findings strongly suggest that restoration of PML expression in non-Hodgkin lymphomas may provide an attractive therapeutic approach." (PMID 23526763, 2013).
ocular melanoma (1 paper, 2024). A melanoma that arises from the structures of the eye or ocular adnexa. "The decreased expression of SP100A further results in the loss of PML bodies, which initiate the progression of ocular melanoma." (PMID 38118002, 2024). "Together, these results suggested that ALKBH3 promotes ocular melanoma through the decrease of SP100A-mediated PML bodies both in vivo and in vitro." (PMID 38118002, 2024). "Consistently, the stable knockdown of SP100A resulted in a compromised expression of PML expression in both wild-type (lanes 1 and 3) and ALKBH3-deficient ocular melanoma cells (lanes 2 and 4)." (PMID 38118002, 2024). "Taken together, these gain-of-function data revealed that SP100A is responsible for the formation of PML nuclear condensates, serving as a tumor suppressor in ocular melanoma." (PMID 38118002, 2024).
papillary renal cell carcinoma (1 paper, 2024). A rare subtype of renal cell carcinoma, arising from the renal tubular epithelium and showing a papillary growth pattern, which typically manifests with hematuria, flank pain, palpable abdominal mass or nonspecific symptoms, such as fatigue, weight loss or fever. "Of note, this analysis showed PML overexpression also in papillary renal cell carcinoma (kidney renal papillary carcinoma; KIRP), albeit to a lesser extent." (PMID 38730056, 2024).
proliferative diabetic retinopathy (1 paper, 2018). Advanced retinopathy due to diabetes mellitus characterized by the formation of new vessels in the retina. "For example, the low levels of PML in proliferative diabetic retinopathy implies that up-regulation of PML might mediate angiostatic effects and ameliorate these symptoms in diabetic patients." (PMID 29416846, 2018).
pyrexia (1 paper, 2024). "Our patient presented with a 2-week history of pyrexia, and initial assessments, including complete blood count, coagulation parameters, bone marrow morphology, and immunophenotyping, strongly suggested a diagnosis of APL with PML::RARA." (PMID 39432585, 2024).
renal cell carcinoma (1 paper, 2024). "Renal cell carcinoma (RCC) is a tumor type where PML functions are still poorly characterized." (PMID 38730056, 2024).
rhabdomyosarcoma (1 paper, 2017). A rare aggressive malignant mesenchymal neoplasm arising from skeletal muscle. "Rhabdomyosarcoma-derived epithelial TE671 cells were similarly knocked out for PML by lentiviral transduction, and knockout was efficient." (PMID 28656178, 2017).
Rotavirus infection (1 paper, 2020). Infection with any of the rotaviruses. "In order to detect which isoform of PML proteins is responsible for counteracting antiviral response against rotavirus infection, PML-II expression was measured using specific primers, the amplification curve was investigated and the threshold was set automatically." (PMID 31677607, 2020).
skin cancer (1 paper, 2024). "For instance, significant cytoplasmic staining for PML proteins was observed in the biopsy of a patient with skin cancer, accompanied by a small number of NBs in the nucleus." (PMID 39395810, 2024). "For instance, examination of skin cancer biopsies reveals a high cytoplasmic expression of PML proteins." (PMID 39395810, 2024).
staphylococcal infection (1 paper, 2020). An infection caused by Staphylococcus. "We found here that mice showed stronger PML and monocyte recruitment and bacterial killing early in dermal staphylococcal infection, if it had been preceded by an intradermal staphylococcal infection three weeks before, indicating that lasting immune priming indeed occurred at the local level." (PMID 32639232, 2020).
T-cell leukemia (1 paper, 2014). A malignant disease of the T-lymphocytes in the bone marrow, thymus, and/or blood. "For example, we have recently used the promyelocytic leukemia (PML) protein, for which the gene is absent in the zebrafish, as a marker of human primary T-cell leukemia cells during ex vivo proliferation analyses." (PMID 24973744, 2014).
ulcerative colitis (1 paper, 2025). An inflammatory bowel disease involving the mucosal surface of the large intestine and rectum. "CHAC1 may participate in the pathogenesis of ulcerative colitis via the miR-214-3p–STAT6 axis, while PML may be regulated by miRNAs with immunomodulatory functions, such as miR-146b-3p." (PMID 41312366, 2025).
viral hepatitis (1 paper, 2012). An acute or chronic inflammation of the liver parenchyma caused by viruses. "Furthermore, TRAIL and its receptors have been shown to be upregulated in the liver of HCV infected patients and PML is a molecule which, as well, is upregulated in inflammatory settings as viral hepatitis." (PMID 22984515, 2012).
ZIKV infection (1 paper, 2022). "Importantly, ZIKV infection reduced the association of SUMO1 with PML and reduced PML expression levels." (PMID 35890062, 2022).
Zinc deficiency (1 paper, 2025). A deficiency of the essential metal Zinc; an essential cofactor for many enzymes. "Increased PML‐RARα degradation by zinc deficiency is also presented by a representative western blot." (PMID 40583520, 2025). "Furthermore, we analysed the presence of the PML‐RARα fusion protein after zinc deficiency." (PMID 40583520, 2025).
tumor (295 papers, 2008 to 2026). "This is similarly observed in a variety of malignancies where SP100 is degraded and loss of PML-NB integrity is associated with tumor progression and immune evasion." (PMID 41188771, 2025). "Ubiquitin-dependent enhanced degradation of PML proteins in humans is associated with tumor progression due to weakened pro-senescence activity." (PMID 40643463, 2025). "Here, we identify USP22 as novel regulator of basal and tumor-associated PML and PML-RARα function, interferon (IFN) regulation and APL differentiation." (PMID 38467608, 2024). "Due to the large number of client proteins modified at PML NBs, these structures have been implicated in the regulation of a wide variety of biological functions, in particular tumor-suppressive functions such as senescence, apoptosis or transcription control." (PMID 38611029, 2024). "The ablation of PML caused a shift in both cell lines toward a more mesenchymal appearance that has been previously linked to increased cell invasiveness and tumor recurrence or metastasis." (PMID 37518985, 2023). "While decreased expression of the PML protein is associated with tumor progression in many types of cancer, some tumors exhibit unexpectedly high levels of PML." (PMID 38069029, 2023). "These modifications have also been associated with tumor progression together with PML ubiquitination and phosphorylation at S402 and S518, and CAP1 phosphorylation by GSK3B at T307, S308 and S31034–37." (PMID 35292711, 2022). "The promyelocytic leukemia (PML) protein is a tumor suppressor that is associated with protein-based condensates in the nucleus called PML bodies." (PMID 36203874, 2022). "In line with this, in response to the loss of PML tumor development is supported by cancer cell-intrinsic autophagy, as a mechanism promoting cell survival during stress conditions." (PMID 36158205, 2022). "The biological function of the gene PML was associated with its nuclear location, and PML was associated with cell cycle regulation and tumor suppression." (PMID 34188683, 2021). "PML, a tumor suppressor, regulates cell-cycle progression of the nervous system as PML loss was found to disrupt neuronal cell differentiation and increase neurogenesis." (PMID 33811862, 2021). "We here report on the implementation and clinical success of our epichaperome-directed diagnostic assay in a patient with refractory AML, which tumor harbored a novel PML-SYK fusion and epichaperome-driven aberrant PPI networks." (PMID 34040147, 2021). "In APL disease, PML‐NBs are disrupted in the cell nucleus with a consequent loss of their tumor‐suppressive activity." (PMID 32328411, 2020). "In some cancer types, high PML expression is associated with telomere shortening for tumor suppression and apoptosis, cell cycle arrest, and senescence, owing to the lack of telomere maintenance." (PMID 32784588, 2020). "PML-null mice are highly susceptible to tumor development when challenged by carcinogens, which highlights the crucial roles of PML in tumor suppression." (PMID 32826889, 2020). "Several lines of research and evidences have elucidated the role of PML in tumor suppression and its concomitant loss in multiple cancers." (PMID 31506431, 2019). "The correlation of tumor abundance as well as PML deficiency as well as downregulated RASSF6 and NLRP12 expression was confirmed in our patient cohort." (PMID 31144474, 2019). "Dysregulation of PML, a significant tumor suppressor is linked with cancers of different histological origins, with a decreased expression observed with a higher tumor grade." (PMID 31506431, 2019).
tumor (continued). "The E3 ligase activity of the ring domain of UHRF1 promotes ubiquitination-mediated degradation of the promyelocytic leukemia (PML) protein, a tumor-suppressor protein implicated in tumorigenesis in multiple forms of cancer." (PMID 29899856, 2018). "Due to its initial association with cancer as a tumor suppressor, early studies on PML have mainly focused on its role in apoptosis, cell cycle regulation and tumorigenesis." (PMID 29416846, 2018). "Manipulation of PML is a key mechanism to regulate tumor-associated angiogenesis and IFN and TNF-mediated angiogenic suppression." (PMID 29416846, 2018). "One possible anti-tumor mechanism of FNC was found to be associated with the regulation of transcriptional activity by the PML pathway." (PMID 28333959, 2017). "As a consequence, cells expressing the tumor suppressor PML were susceptible to engage apoptosis upon cell stress or damage and to maintain an adequate production of ATP, preventing the growth of damaged or malignant cells." (PMID 28725634, 2017). "The tumor suppressive functions of PML in CML are associated with the differential PML expression during the leukemic differentiation." (PMID 27184141, 2016). "Although the PML gene is rarely mutated in cancer, its protein expression is lost in a number of human tumors, suggesting that it acts as tumor suppressor." (PMID 23760585, 2013). "Which of the multiple functions of PML is crucial or contrasts cancer development and maintenance depends probably on the specific physiological state of each neoplasia, and it is determined by the mutations occurring in that specific cell." (PMID 23847764, 2013). "Loss or down-regulation of these proteins causes PML stabilization and tumor suppression by senescence induction in human primary fibroblasts or in cancer cells (45, –47)." (PMID 23847762, 2013). "More importantly, high PML mRNA and protein expression was significantly associated with triple-negative breast cancer tumor subtype, high tumor grade, early tumor recurrence, and poor prognosis." (PMID 23936764, 2013). "Several studies have investigated the underlying mechanisms for NBs-loss during tumor progression and have implicated PML degradation, more than loss of PML gene expression." (PMID 23847762, 2013). "Consistent with its known tumor suppressor role, we identified Cancer as the largest category of disease associated with PML." (PMID 22947142, 2012). "Accordingly, loss of PML bodies has been associated with the development and/or progression of several tumours." (PMID 23170171, 2012). "We also found PML to be linked to cancer metastasis as identified by an association with Neoplasm metastasis." (PMID 22947142, 2012). "In total, 35 samples (71.4%) showed partial-to-complete loss of PML in the tumor cell nuclei of stage IV advanced gastric carcinomas." (PMID 22022583, 2011). "Nuclear PML protein has been implicated in cell growth, tumor suppression, apoptosis, transcriptional regulation, chromatin remodeling, DNA repair, and anti-viral defense." (PMID 18509536, 2008). "Although these results suggest that the transition from an immortalised to a tumour phenotype is linked to dysregulation of the hsa-miR-620/PML axis, it is necessary to perform functional assays to more accurately validate this hypothesis." (PMID 41597397, 2026). "Similarly, RAB27A and S100P are two genes linked to tumor development that are located within APL-specific enhancers that also harbor multiple PML-RARA binding sites and where enhancer interactions are dependent on the PML-RARA protein." (PMID 41168841, 2025).
tumor (continued). "Furthermore, NUP358 facilitates SUMOylation of promyelocytic leukemia protein (PML) transcript variant IV, favoring PML nuclear body formation and PML-IV function, and therefore plays a tumor suppressive role in CRC cells." (PMID 39080077, 2024). "The gene encoding promyelocytic leukemia (PML), a tumor suppressor primarily expressed in the nucleoplasm, interacts directly or indirectly with TERT in HepG2, U2OS, and HFF cell lines, negatively regulating telomerase activity and eventually resulting in telomere shortening." (PMID 38278800, 2024). "In addition, PML loss changed the MCF7 tumor spheres from their known smooth spherical morphology to a more grape one, reflecting a change in the expression of cell–cell interacting proteins." (PMID 37518985, 2023). "While PML silencing of all PML isoforms in those cell types caused a slight increase in the cell growth rate in monolayer culture, their tumor sphere ability was compromised (25–30% of the control line) implying a role for PML in their maintenance of stem‐cell‐like properties." (PMID 37518985, 2023). "Finally, PML loss also induces mitochondrial defects and cytokine production in the microenvironment to boost tumor growth and impair therapy response." (PMID 37382966, 2023). "Although PML mRNA is expressed in most cell types and the PML gene is rarely mutated or deleted from the genome, PML protein expression is often suppressed in human cancer and frequently correlates with tumor grade and progression." (PMID 38069029, 2023). "In addition, PML loss promotes hypoxia–angiogenic switch that favors local and metastatic growth as well as the long‐term maintenance of tumor‐initiating cells." (PMID 37518985, 2023). "A few pioneer studies have exemplified fusion-circRNAs (f-circRNAs) derived from tumor-associated chromosomal translocations, such as PML-RARα, MLL-AF9, EWSR1/F LI1, and EML4/ALK1, and these f-circRNAs were circularized by transcribed exons of distinct genes affected by the translocations." (PMID 36613512, 2022). "In terms of molecular function, they have serine/threonine protein kinase activity can regulate different molecular pathways in normal and tumour cells and are involved in the development of cancer.At the cellular component level, these target genes are significantly associated with the PML body." (PMID 36104345, 2022). "PML protein is the core component of multifaceted subnuclear structures known as PML nuclear bodies (PML NBs) that are implicated in the regulation of cellular functions including cell proliferation, apoptosis, senescence, tumor suppression, DNA repair, and DNA damage responses." (PMID 34360546, 2021). "In keeping with these results, loss of specific tumor suppressors, such as promyelocytic leukemia protein (PML) or tuberous sclerosis proteins 1 and 2 (TSC1 and TSC2), has been shown to promote HIF-1α expression through suppression of hypoxia-induced inhibition of mTOR." (PMID 31530290, 2019). "Furthermore, this study implicates that the response of tumor cells characterized by loss of PML to chemotherapeutic agents can be improved by inhibiting autophagy." (PMID 29491433, 2018). "The tumor suppressor function of PML NBs may be linked to their ability to accumulate many proteins involved in DNA damage response and repair pathways, which is believed to stabilize DNA repair complexes and enhance their activities." (PMID 29888200, 2018). "Thus, one possible anti-tumor mechanism of FNC was found to be associated with the regulation of transcriptional activity by the PML pathway." (PMID 28333959, 2017).